AMY2B (amylase alpha 2B)
Synonyms: AMY2; AMY3; HXA
Tractability: Small molecule: it belongs to a druggable protein family. Antibody: UniProt places it where antibodies can reach, with medium confidence; UniProt predicts a signal peptide or a membrane-spanning region; its Gene Ontology location is reachable by antibodies, with medium confidence.
Gene: Protein-coding gene on chromosome 1 (103,553,815 to 103,579,534, forward strand). Ensembl gene ENSG00000240038.
Subcellular location: Secreted
Subcellular location (Human Protein Atlas): Cytosol; Golgi apparatus; Predicted to be secreted
Pathways (Reactome):
Digestion and absorption: Digestion of dietary carbohydrate
Gene Ontology:
Molecular function: alpha-amylase activity; calcium ion binding; catalytic activity; cation binding; chloride ion binding
Biological process: carbohydrate metabolic process
Cellular component: extracellular exosome; extracellular region
Genetic constraint (gnomAD): Loss-of-function variants: 68 observed, 59.63 expected, observed/expected ratio (o/e) 1.14, 90% interval 0.94 to 1.39. The upper end of that interval is the gene's LOEUF score, 1.39, which puts it in group 5 of 6, group 1 being the genes least tolerant of losing a copy. Missense variants: 635 observed, 604.1 expected, observed/expected ratio (o/e) 1.05, 90% interval 0.98 to 1.12. Synonymous variants: 180 observed, 195.31 expected, observed/expected ratio (o/e) 0.92, 90% interval 0.81 to 1.04.
Homologues: Orthologues: chimpanzee AMY2B (99% identical), macaque AMY2B (95% identical), tropical clawed frog amy2a (77% identical), tropical clawed frog amy2b (75% identical), Drosophila melanogaster Amy-p (53% identical), Drosophila melanogaster Amy-d (52% identical), Drosophila melanogaster Amyrel (47% identical), Caenorhabditis elegans C50B6.7 (47% identical), Drosophila melanogaster Mal-A7 (15% identical), Drosophila melanogaster Mal-A4 (15% identical), Drosophila melanogaster Mal-A8 (14% identical), Drosophila melanogaster Mal-B2 (14% identical), and 4 more. Paralogues in human: AMY2A (99% identical), AMY1A (97% identical), AMY1B (97% identical), AMY1C (97% identical), SLC3A1 (18% identical), GBE1 (15% identical), SLC3A2 (13% identical).
Diseases named in the same sentence as AMY2B in open-access papers:
AMY2B is named in the same sentence as 18 diseases in open-access papers, as found by Europe PMC text mining. Sharing a sentence is not in itself a finding about the gene and the disease. The quoted sentences say what the papers report.
breast carcinoma (3 papers, 2014 to 2025). "Our data show that AMY2B exhibits a low expression pattern in the breast cancer microenvironment, providing new insights into the potential role of the amylase family in breast cancer development." (PMID 41275376, 2025). "Interestingly, although previous studies reported reduced AMY2B expression in various tumors, it has not been thoroughly explored in breast cancer." (PMID 41275376, 2025).
chronic pancreatitis (1 paper, 2022). A chronic inflammatory process causing damage and fibrosis of the pancreatic parenchyma. "For example, clusterin (CLU) plays an essential role in pancreas regeneration and is expressed in chronic pancreatitis; α-amylase (AMY2B) is a characteristic gene for mature acinar cells, encoding a digestive enzyme." (PMID 35758781, 2022).
COVID-19 (1 paper, 2024). A disease caused by infection with severe acute respiratory syndrome coronavirus 2. "Evidently, the levels of AMY2A and AMY2B were relatively higher in survivors of COVID-19 compared to those who died of COVID-19." (PMID 38575325, 2024).
Hyperglycemia (1 paper, 2020). An increased concentration of glucose in the blood. "With OLAN treatment, in addition to its induction of INPP5D, the suppression of AMY2B and GNAI1 are predicted to increase hyperglycemia and decrease insulin sensitivity." (PMID 33302598, 2020).
Obesity (1 paper, 2015). Accumulation of substantial excess body fat. "Similarly, direct genotyping of AMY2B in dogs may be useful in preventing and managing obesity." (PMID 26683458, 2015).
spinal muscular atrophy (1 paper, 2025). A motor neuron disease that affect the muscles, and characterized by muscle weakness and atrophy resulting from progressive degeneration and irreversible loss of the anterior horn cells in the spinal cord (i.e., lower motor neurons) and the brain stem nuclei. "We found reduced expression of SMN2 due to SMN1 conversion, potentially affecting spinal muscular atrophy, and increased expression of translocated duplications of AMY2B." (PMID 39149335, 2025).
systemic lupus erythematosus (1 paper, 2015). An autoimmune multi-organ disease typically associated with vasculopathy and autoantibody production. "For example, FCGR3A, FCGR2B and HLA-DQA1 may function via the systemic lupus erythematosus pathway, and AMY2B and AMY2A may participate in lung SCC via starch and sucrose metabolism pathway." (PMID 26297502, 2015).
tumor (3 papers, 2014 to 2024). "The specificity of this analysis was supported by the downregulation of the acinar and insular cell markers AMY2B and INS, while the expression of the tumor marker KRT19 was increased (Fig. EV3A)." (PMID 38413734, 2024).
AMY2B also shares sentences with these, for which no sentence is quoted: diabetes mellitus (2 papers); amyloidosis (1); infection (1); influenza (1); lung carcinoma (1); malignant brain tumors (1); neutropenia (1); ovarian carcinoma (1); pancreatic cancer (1); prostate carcinoma (1).